MLKL (mixed lineage kinase domain like pseudokinase)
Diseases named in the same sentence as MLKL in open-access papers (continued):
Sharing a sentence is not in itself a finding about the gene and the disease.
acute kidney injury (14 papers, 2016 to 2025). Sudden and sustained deterioration of the kidney function characterized by decreased glomerular filtration rate, increased serum creatinine or oliguria. "Consistent with this, deficiency of RIPK3 or MLKL prevents oxalate crystal-induced acute kidney injury." (PMID 26817517, 2016). "RIPK1 KD mutants, RIPK3, and MLKL deficiency could alleviate acute kidney injury by decreasing necroptosis." (PMID 34977874, 2021). "Both in vivo and in vitro results indicated that ALR has a protective effect against acute kidney injury caused by ischemia-reperfusion, and the RIP1/RIP3/MLKL pathway should be further verified as a probable necroptosis regulating mechanism." (PMID 35164651, 2022). "We established an ischemia-reperfusion model through in vivo and in vitro experiments to confirm that ALR can regulate necroptosis through the RIP1/RIP3/MLKL pathway, thereby alleviating acute kidney injury." (PMID 35164651, 2022). "In summary, our results demonstrate for the first time that kidney-specific knockout of ALR aggravates IR-induced acute kidney injury, and that ALR can ameliorate IR-induced acute kidney injury by regulating necroptosis through the RIP1/RIP3/MLKL pathway." (PMID 35164651, 2022). "We conclude that crystal-induced cytotoxicities of human and murine kidney cells are comparable and that human tubular epithelial cells also activate MLKL in the context of oxalate crystal-induced acute kidney injury." (PMID 26817517, 2016). "The authors conclude that 3-MCPD can induce renal toxicity, inducing tubular cell death by activating the RIPK1/RIPK3/MLKL-related necroptosis pathway, generating acute kidney injury, and activating the programmed cell death pathway of tubular cells in kidney tissue." (PMID 40137488, 2025). "The expression of RIP1/RIP3/MLKL increased in acute kidney injury induced by IR." (PMID 35164651, 2022). "Also in human oxalate crystal-related acute kidney injury, dying tubular cells stain positive for phosphorylated MLKL." (PMID 26817517, 2016). "Changes in the PANoptosis-related proteins BCL2, Bax, ASC, RIP3, and MLKL were measured in WT and Nrf2−/− mice treated with AME for the treatment of cisplatin-induced acute kidney injury." (PMID 40110131, 2025). "Among the investigated pathologies, necroptosis also demonstrates its implication in kidney diseases; indeed, both acute kidney injury (AKI) and chronic kidney disease (CKD) report increased levels of RIPK1, RIPK3, and MLKL, suggesting necroptosis as a crucial event in kidney injuries." (PMID 35682876, 2022).
gastric cancer (14 papers, 2018 to 2024). A primary or metastatic malignant neoplasm involving the stomach. "Gentiopicroside enhanced p-RIPK3/RIPK3 protein levels and p-MLKL/MLKL protein levels, suggesting the activation of necroptosis in gastric cancer SGC7901 cells." (PMID 39570876, 2024). "MLKL is an important component of necroptosis, and has been proved to be closely related to the prognosis of gastric cancer (GC)." (PMID 36010886, 2022). "Furthermore, celastrol activated receptor-interacting protein 1 and 3 (RIP1 and RIP3) and subsequently promoted the translation of mixed-lineage kinase domain-like (MLKL) from cytoplasm to plasma membrane, leading to necroptosis of gastric cancer cell, which was blocked by over-expression BGN." (PMID 31739592, 2019). "Thus, by blocking MLKL-mediated necroptosis, gastric cancer cells might maintain tumor cell growth." (PMID 36035126, 2022). "Taken together, we identified celastrol as a necroptosis inducer, activated RIP1/RIP3/MLKL pathway and suppressed the level of pro-inflammatory cytokines by down-regulating BGN in HGC-27 and AGS cells, which supported the feasibility of celastrol in gastric cancer therapy." (PMID 31739592, 2019).
liver fibrosis (14 papers, 2020 to 2025). "Blockage of S1PR2/ZBP1/p-MLKL axis caused the decrease of necroptosis, and importantly, the attenuation of liver fibrosis." (PMID 36859525, 2023). "Here we sought to elucidate the function of MLKL in liver fibrosis and underlying mechanisms." (PMID 35836819, 2022). "Taken together, these data show a clear and strong positive correlation between MLKL and liver fibrosis, indicating that MLKL may play a role in this pathogenic process." (PMID 35836819, 2022). "The discovery that knocking out Mlkl specifically in endothelial cells alleviates liver fibrosis in a mouse MASH model underscores the importance of comprehending the cell-type-specific effects of MLKL in order to discern its role in MASH." (PMID 38474061, 2024). "Collectively, these findings suggest that the fibrotic response in MlkliΔEC/iΔEC mice is downregulated in the NASH model, indicating that MLKL plays an important role in the progression of liver fibrosis." (PMID 37511074, 2023). "More importantly, selective knockdown of S1pr2, Zbp1 or Mlkl in macrophage decreased ZBP1/p-MLKL-mediated necroptosis, and further attenuated liver fibrosis in BDL-induced cholestatic liver injury." (PMID 36859525, 2023). "We next employed Zbp1 siRNA-GeRPs to further confirm the importance of ZBP1/p-MLKL-mediated necroptosis in liver fibrosis." (PMID 36859525, 2023). "Our study for the first time demonstrated the vital role of macrophage necroptosis mediated by ZBP1/p-MLKL to the pathology of BA liver fibrosis." (PMID 36859525, 2023). "Selective blockage of S1PR2/ZBP1/p-MLKL axis in macrophage attenuated necroptosis and liver fibrosis in BDL mice." (PMID 36859525, 2023). "Methods and Results: Here we report that MLKL level is positively correlated with a number of fibrotic markers in liver samples from both patients with liver fibrosis and animal models." (PMID 35836819, 2022). "Although necroptosis has been reported to play an important role in a number of liver diseases, the function of MLKL in liver fibrosis has yet to be unraveled." (PMID 35836819, 2022). "Collectively, these results demonstrate that MLKL contributes to the initiation and progression of liver fibrosis." (PMID 35836819, 2022). "Necroptosis mediated by MLKL is closely tied to liver fibrosis." (PMID 39669199, 2024). "Our results help in better understanding the role of GDCA/S1PR2/ZBP1/p-MLKL mediated macrophage necroptosis in cholestatic liver diseases, and might provide novel therapeutic strategies to attenuate BA liver fibrosis." (PMID 36859525, 2023). "Targeting MLKL may be a successful strategy for treating liver fibrosis because MLKL-mediated signalling plays a significant role in liver damage and fibrosis." (PMID 37910384, 2023). "Notably, EC-specific ablation of MLKL effectively attenuates liver fibrosis in NASH by blocking necroptosis and mitigating the TGFβ/Smad 2/3 signaling axis between endothelial cells and HSCs." (PMID 37511074, 2023). "Moreover, in consistent with BA livers, we also detected p-MLKL+ZBP1+ macrophages (F4/80+ cells) in BDL-induced mouse liver fibrosis." (PMID 36859525, 2023). "In conclusion, GDCA/S1PR2/ZBP1/p-MLKL mediated macrophage necroptosis plays vital role in the pathogenesis of BA liver fibrosis, and targeting this process may represent a potential therapeutic strategy for BA." (PMID 36859525, 2023). "In conclusion, all these results showed that blockage of GDCA/S1PR2/ZBP1/p-MLKL axis-mediated necroptosis, which was an important player of cholestatic liver fibrosis, could be potential target of BA liver fibrosis." (PMID 36859525, 2023). "Further research has shown that AAV8-mediated knockdown of MLKL, which is the ultimate effector of the necroptosis signal pathway, significantly attenuates CCl4-induced hepatic fibrosis, indicating that MLKL-modulated necroptosis plays an essential role in liver disease and fibrosis." (PMID 38086792, 2023).
liver fibrosis (continued). "Our results demonstrate targeting MLKL in hepatocytes might be an effective way to treat liver fibrosis." (PMID 35836819, 2022). "In A-KO mice, in addition to decreased expression of liver fibrosis-related genes, the Ripk3 and Tnf genes, as well as RIPK3 protein expression and RIPK3 and MLKL phosphorylation, were decreased compared with control mice." (PMID 36690638, 2023). "We found that endothelial cell (EC)-specific knockout of mixed lineage kinase domain-like protein (MLKL), a critical executioner involved in the disruption of cell membranes during necroptosis, alleviated liver fibrosis in the mouse NASH model." (PMID 37511074, 2023). "In BDL-induced liver fibrosis, selectively knocking down of macrophage S1pr2, Zbp1 or Mlkl blocked S1PR2/ZBP1/p-MLKL axis." (PMID 36859525, 2023). "By impeding necroptosis-associated inflammatory signalling, MLT reduced these increases and prevented liver fibrosis by downregulating RIPK1 and MLKL." (PMID 37910384, 2023). "Besides, we also employed necroptosis inhibitor targeting MLKL (Necrosulfonamide, NSA) to explore the role of necroptosis in liver fibrosis following recent publications." (PMID 36859525, 2023). "Furthermore, this process was mediated by ZBP1/p-MLKL, and the upregulated expression of ZBP1 in BA livers was correlated with liver fibrosis and prognosis." (PMID 36859525, 2023). "Moreover, p-MLKL was found to be co-localised with SMA, further supporting the correlation between necroptosis inhibition and hepatic fibrosis." (PMID 33462187, 2021).
Cerebral ischemia (13 papers, 2017 to 2025). Restriction of arterial blood supply to the brain associated with insufficient oxygenation to support the metabolic requirements of the tissue. "In contrast with wild‐type mice, RIPK1 kinase‐dead mice, RIPK3 deficient mice, and MLKL deficient mice showed reduced levels of cell necrosis and neuroinflammation after cerebral ischemia, which is highly consistent with the apoptotic pathway of necrotic cells." (PMID 39657719, 2024). "Thus, TRAF2 induction likely inhibits cerebral ischemia-induced necroptosis through increased complex formation with MLKL, consequently inhibiting the association between MLKL and RIP3." (PMID 30988281, 2019). "During VCI cerebral ischemia, MLKL is phosphorylated and translocates to the plasma membrane, leading to an influx of Ca2+ and Na+ ions, which immediately opens the mPTP." (PMID 40636901, 2025). "Studies have reported that the activation of receptor-interacting protein kinase (RIPK)-mixed lineage kinase domain-like protein (MLKL) signaling pathway is involved in the onset of neuronal necrosis after injury by cerebral ischemia." (PMID 35317197, 2022). "The knockdown of MLKL with siRNA in CA1 after tGCI effectively reduces MLKL and p-MLKL expression and attenuates neuronal death in CA1 after cerebral ischemia, whereas overexpression of MLKL with lentiviral delivery of MLKL showed opposite results." (PMID 33879157, 2021). "NSA administration inhibits the expression of mixed lineage kinase domain-like (MLKL) through the ubiquitination proteasome pathway and then greatly reduces infarct volume and improves neurological recovery after cerebral ischemia-reperfusion." (PMID 32089771, 2020). "To investigate the molecular mechanisms underlying the protective role of TRAF2 in cerebral ischemia, we assessed the levels of RIP1, RIP3 and MLKL following MCAO." (PMID 30988281, 2019). "To conclude, TRAF2 likely serves as a suppressor for cerebral ischemia-induced necroptosis through interaction with MLKL." (PMID 30988281, 2019). "In this study, we examined MLKL expression after cerebral ischemia reperfusion injury using a middle cerebral artery occlusion (MCAO) mouse model." (PMID 28978125, 2017). "The results demonstrated that ischemic brain injury increased MLKL expression at the early stage of cerebral ischemia." (PMID 28978125, 2017). "Additionally, BCP has been observed to attenuate neuronal necrosis and the expression of receptor-interaction protein kinase-1 (RIPK1), receptor-interaction protein kinase-3 (RIPK3) and mixed-lineage kinase domain-like protein (MLKL) in cerebral ischemia." (PMID 38542177, 2024). "Our data suggest that (i) p-RIPK1 (Ser166) participated in RIPK3/MLKL-dependent neuronal necroptosis after cerebral ischemia; (ii) immunostaining with a specific antibody against p-RIPK1 (Ser166) could be used as a morphological biomarker for necroptosis." (PMID 31440386, 2019). "Therefore, we speculate that this time-dependent switch of MLKL to microglia reflects the pathological changes of cerebral ischemia and can contribute to the development of secondary injury." (PMID 33879157, 2021). "The expression of necroptosis kinases, including MLKL/p-MLKL, RIPK3/p-RIPK3, and RIPK1/p-RIPK1, was significantly increased in the brain tissue of an OGD-induced neuronal injury model and the brain tissue of cerebral ischemia animal models." (PMID 40636901, 2025). "We found that cerebral ischemia stimulated phosphorylation of RIPK1 at the Ser166 residue and increased RIPK3 and MLKL expression levels in the brain." (PMID 31440386, 2019). "However, it is unknown whether MLKL expression is changed after cerebral ischemia injury." (PMID 28978125, 2017). "Moreover, the levels of neuronal necrotizing factors and colocalization of NeuN and MLKL were also increased in middle cerebral artery occlusion (MCAO) mice, indicating that necroptosis is involved in neuronal death in cerebral ischemia." (PMID 40636901, 2025).
COVID-19 (13 papers, 2021 to 2025). A disease caused by infection with severe acute respiratory syndrome coronavirus 2. "The hallmark of necroptosis, p-MLKL, has been detected in the lung section of COVID-19 patients and SARS-CoV-2-infected human ACE2 transgenic mice." (PMID 39872161, 2022). "In COVID-19, the necroptosis pathways of MLKL-, fas-associated death domain (FADD)-, and apoptosis-associated speck-like protein containing a caspase recruitment domain (ASC)-related genes are likely to be involved in lymphopenia and might potentially predict the COVID-19 outcome." (PMID 38001795, 2023). "Targeting of MLKL, or other methods of interfering with necroptosis, are unlikely to represent therapeutic avenues for the management of COVID-19." (PMID 38286985, 2024). "In the lung tissues of the animal model of severe COVID-19, the levels of phospho-MLKL and cleaved GSDMD, executioners of necroptosis and pyroptosis, respectively, were significantly elevated compared with the other two groups." (PMID 36507222, 2023). "The protein levels of RIPK1, RIPK3, and MLKL are also elevated in the plasma of both moderate and severe COVID-19 patients." (PMID 39872161, 2022). "On the other hand, the expression of MLKL was highly upregulated in the severe COVID-19 lung and was detected in lung and airway epithelial cells as well as macrophages and neutrophils." (PMID 34663909, 2021). "Cells stimulated with TNF-α and IFN-γ show MLKL and RIPK1 phosphorylation, suggesting that necroptosis is implicated in the COVID-19 cytokine storm." (PMID 34594225, 2021). "Phospho-MLKL and caspase-3 are increased in platelets of patients with COVID-19, showing that the necroptosis and apoptosis of platelets mediate a rapid response to SARS-CoV-2." (PMID 34594225, 2021). "Furthermore, recent studies have identified phosphorylated MLKL (p-MLKL) expression in the septic adrenal tissues of COVID-19 patients, suggesting a potential pathological link between necroptosis and adrenal dysfunction." (PMID 40430756, 2025). "In our model of severe COVID-19, MLKL-deficiency did not alter the host response, ameliorate weight loss, diminish systemic pro-inflammatory cytokines levels, or prevent lethality in aged animals." (PMID 38286985, 2024). "Finally, our data support the notion that inhibition of MLKL can be a possible new therapeutic or adjunct therapeutic approach to prevent the acute and long-term MACE caused by cardiac injury during severe COVID-19." (PMID 37081485, 2023). "Importantly, MLKL is a biomarker of necroptosis in the hearts of COVID-19 patients and a therapeutic target for major adverse cardiac events." (PMID 38001795, 2023). "Since MLKL is inducible by IFNγ in inflammatory hepatitis to promote inflammation in a RIPK3-independent fashion, MLKL may be induced by the inflammatory response in the COVID-19 lungs." (PMID 34663909, 2021). "Since the phosphorylation of MLKL is mediated by RIPK3 in necroptosis, the low-level expression of RIPK3 in COVID-19 lung may preclude the activation of MLKL downstream of activated RIPK1 to promote necroptosis." (PMID 34663909, 2021). "Interestingly, while neither the active/phosphorylated forms of RIPK3 nor MLKL were detectable in lungs of COVID-19 patients in this study, high gene expression levels of MLKL were identified in lung and airway epithelial cells, macrophages and neutrophils." (PMID 35244141, 2022). "In addition, they observed by immunofluorescence the colocalization of SARS-CoV-2 with phospho-MLKL (mixed lineage kinase domain-like pseudokinase) and caspase 3 in nonpermeabilized platelets in vitro and COVID-19 platelets." (PMID 35842415, 2022). "This provides evidence that MLKL activation in COVID-19 may not occur downstream of activated RIPK1–RIPK3 to promote necroptosis, but rather by alternative RIPK3-independent inflammatory responses such as via IFNγ as previously reported in inflammatory arthritis." (PMID 35244141, 2022).
COVID-19 (continued). "The internalization of SARS-CoV-2 by platelets, either in vitro or in COVID-19 patients, results in the colocalization of SARS-CoV-2 with phosphorylated mixed lineage kinase domain-like protein (phospho-MLKL), a mediator of necroptosis, and caspase-3 on nonpermeabilized platelets." (PMID 35265086, 2022).
Hepatic steatosis (13 papers, 2019 to 2025). Steatosis is a term used to denote lipid accumulation within hepatocytes. "Inhibiting proteins involved in necroptosis, such as RIPK1 and MLKL, has also shown potential in improving liver steatosis and insulin resistance, critical aspects of MASLD." (PMID 38540172, 2024). "We found that chronic plus binge ethanol feeding increased hepatic RIP3 and MLKL as well as hepatic steatosis, which exacerbated IR injury with increased neutrophil infiltration." (PMID 35173541, 2022). "Accumulating evidence illustrated the relevance of key necroptosis signalling molecules including RIPK3 and MLKL, and hepatic steatosis." (PMID 35083817, 2022). "Additionally, IRI damage is increased in pre-damaged steatotic livers, as liver steatosis exacerbates hepatic IR injury through increased MLKL-mediated necroptosis both in in vivo and in vitro models." (PMID 38540172, 2024). "MLKL blocks autophagy and consequently contributes to non‐alcohol‐related fatty liver disease." (PMID 37475188, 2023). "The correlation between RIPK3 and hepatic steatosis is well established, and RIPK1/MLKL axis appears to be a considerable pathway of hepatic lipid deposition." (PMID 35083817, 2022). "Both MLKL and RIPK3 are promising therapeutic targets to inhibit necroptosis during ischaemic injury in fatty liver." (PMID 33435617, 2021). "Therefore, HBx and AFB1 mediated COX‐2 up‐regulation was required for MLKL to be recruited to RIP3 for subsequent execution of necroptosis, and COX‐2 could serve as a potential therapeutic target for necrotic cell death‐associated hepatic steatosis." (PMID 31282064, 2019).